CCL5 (C-C motif chemokine ligand 5)
Diseases named in the same sentence as CCL5 in open-access papers (continued):
Sharing a sentence is not in itself a finding about the gene and the disease.
infection (continued). "We were intrigued to observe that infection of SK-N-SH cells with both ZIKV strains in the presence of 50 μM LXR 623 resulted in significantly higher mRNA expression levels for CXCL10, CCL5 / RANTES and IFN-β1." (PMID 34162308, 2021). "Particularly, infection upregulated the cytokines IFN-γ, IL-12b, and IL-2 (126-, 44-, and 18-fold change, respectively) and the T-cell chemoattractants CCL3 and CCL5 (23- and 16-fold change, respectively)." (PMID 34381739, 2021). "We demonstrated that miR‐146a inhibits the pro‐inflammatory chemokines IL‐8, CXCL1, and CCL5, induces the production of IFN‐λ, and has the capacity to limit infection by RV‐A16 in HBECs." (PMID 34185416, 2021). "Infection of Usp18−/− peritoneal macrophages with EMCV also led to a decrease in fold change of Ifnb and its downstream Ccl5 gene mRNA levels as well as the production of IFN-β compared with the WT counterparts." (PMID 34016972, 2021). "In tissues treated prior to infection, baseline production of IL-1β, IL-22, CCL3, CCL4 and CCL5 varied between BaL- and LAI-infected explants, possibly reflecting virus difference in cell tropism and subsequent CD4 T cell depletion." (PMID 34835109, 2021). "As expected, MVA-infection strongly induced secretion of type 1 interferons (IFN-I) and the IFN-stimulated gene products CXCL10 and CCL5 in macrophages, as well as IL-6, TNF, and GM-CSF." (PMID 34711816, 2021). "Inhibition of miR-548d-3p reduced parasite growth early after infection and increased production of MCP1/CCL2, RANTES/CCL5, and IP10/CXCL10." (PMID 34178725, 2021). "VSV infection significantly induced the expression of seven chemokines (CCL3, CCL4, CCL5, CCL20, CXCL1, CXCL2, and CXCL3) by ~3- to 42-fold compared to mock infection." (PMID 34578166, 2021). "During this infection, the penetration of HIV into hepatic cells is inhibited following the interaction of the chemokine PF-4 (CXC4) as well as RANTES (CCL-5) secreted by platelets." (PMID 34970260, 2021). "There was induction of a variable cytokine response in respiratory tissues at different days post-infection (dpi), including TNF-α, IFN-β, IL-4, IL-6, CXCL8 (IL-8), IL-10, IL-13, CXCL10 (IP-10), CCL5 (RANTES), CXCL9 (MIG), and CCL2 (MCP-1)." (PMID 34452505, 2021). "Downregulation of multiple pro-inflammatory genes (CCL5, IL6, IL1B) was accompanied by upregulation of anti-inflammatory TNFAIP3 at 48 h post-infection." (PMID 34759825, 2021). "IL-22 can act synergistically with TNFα in response to infection-promoting chemokine expression (including CXCL9, CXCL10 and CCL5) by human keratinocytes." (PMID 34207946, 2021). "In the very early stage of infection, chemokines such as IL-8 (CXCL8), MCP-3 (CCL7), and RANTES (CCL5) are produced by numerous cell types." (PMID 33483611, 2021). "What is more, we found out that the levels of IL1β, IL8, RANTES (CCL5), MCP-2, and IGF1 were significant higher in early stage of infection." (PMID 35095832, 2021). "A pronounced innate immune response to infection followed the peak of viral replication, evidenced by induction of cytokines (IL‐6, TNF), chemokines (CCL2, CCL5) and type I and III IFNs (IFNβ, IFNλ1/3) measured by RT–qPCR (and EV2D–F)." (PMID 34101213, 2021). "ZIKV transcriptionally induces CCL5 as well as IFN-β and IFN-λ from infected hBMECs; however, only CCL5 is found to be secreted during infection." (PMID 34399621, 2021). "Following USUV infection, we showed secretion of CXCL10, CCL5, and IL6 in apical compartments from 4 to 10 dpi, but the secretion level decreased with time." (PMID 32324736, 2020). "Upon infection with influenza virus, production of cytokines and chemokines including CCL3, CCL4, and CCL5 from respiratory epithelium recruits γδ T cells at the site of infection in a CCR5 receptor-dependent fashion." (PMID 33183352, 2020). "In the spleen, levels of CCL5/RANTES and IFN-γ were increased and sustained in surviving poly(I:C)-treated animals for 14 days after infection." (PMID 31952519, 2020).
infection (continued). "CCL5 and CCL3 are both chemotactic cytokines that specifically attract T-cells and macrophages to the site of infection." (PMID 32752138, 2020). "On day 5 post infection the Th2 cytokine IL-5 and the pro-inflammatory cytokine IL-6 were massively upregulated in IFN-γOFF mice as well as G-CSF and CCL-5 when compared with infected WT controls." (PMID 32023327, 2020). "After the infection of mice with HSV-1, the expression levels of Ifnb, Ccl5, and Isg15 were significantly lower in the spleens, livers, and lungs of Arrb2−/− mice than in those of WT mice." (PMID 33243993, 2020). "After early neutrophil (2 h.p.i.)and monocyte (6 h.p.i.)chemoattractants secretion, eosinophil chemoattractants—CCL5 (RANTES) and CCL11 (eotaxin)—secretion follows while the hRSV infection continues, the latter occurring around 12 h.p.i.." (PMID 32545470, 2020). "Results from qRT-PCR analysis showed that the expression of Ifnb, Il6, and Ccl5 in the hearts and brains of Rnf115−/− mice was higher than that of wild-type littermates at day 4 after EMCV infection." (PMID 33139700, 2020). "Conversely, expression of IE1dl410-420 led to a marked increase in infection-related induction of the IFNB1, IFNL1, CCL5, TNF and PML genes." (PMID 32365141, 2020). "Infection with RV1B induced a marked increase in IL-8 (17-fold over untreated), IL-6 (7-fold) and CCL5 (33-fold)." (PMID 32117246, 2020). "Several chemokines, including IP-10 (CXCL10), CCL2 (MCP-1), CCL3 (MIP-1α), CCL4 (MIP-1β), CCL5 (RANTES), and CCL7 (MCP-3) were also significantly increased upon infection." (PMID 32373101, 2020). "Contrasting results were observed in a study which reported a comparatively higher innate immune response to YF-17D than Asibi, but that study measured chemokines (CCL5, CXCL10) instead, which act by attracting phagocytic cells to sites of infection." (PMID 32722523, 2020). "In this analysis, the highest upregulation was observed for CCL5/RANTES and CSF1 in both CVS-11 and Z.Dog rabies infection, compared with mock infection." (PMID 32218146, 2020). "IE1cc172-176 expression resulted in significantly reduced induction of transcripts from the IFNB1, IFNL1, CCL5 and TNF genes relative to the wild-type protein following infection." (PMID 32365141, 2020). "As mentioned, we found that the expression of CXCL1, CXCL12, CCL2, CCL5 and TIMP-1 was significantly increased upon CGS-17 and CXZ-15 infection." (PMID 33081802, 2020). "We found that the expression of CCL2, CCL5, IL-6, and TNF-α was inhibited through the course of infection in U0126-pretreated cells and that viral RNA abundance was also decreased in U0126-pretreated cells." (PMID 31694957, 2020). "When the siRNAs HRSV-F, TRIM25/HRSV-F, or the combination of TRIM25 plus HRSV-F were transfected before infection, the levels of IL6, CCL5, and IFN-β mRNAs increased significantly at 24 hpi." (PMID 31035368, 2019). "Since infection-primed ADAPko NK cells exhibited impaired production of the phagocyte attracting chemokines CCL3, CCL4, and CCL5 we compared the number of monocytes and neutrophils in the spleen of Lm infected animals." (PMID 32038647, 2019). "A single metabolite, the chemokine RANTES (CCL5), was exclusively affected in the cerebellum, where both infection groups showed elevated levels during the subacute and chronic phase of NT." (PMID 31315623, 2019). "NK cell recruitment to the site of infection depends on expression of chemokine receptors, namely, CCR2, CCR5, and CXCR3 through interaction with ligands like CCL2, CCL5, CXCL9, CXCL10, and CXCL11." (PMID 31612153, 2019). "Compared to mock infection, RSV infection via both inoculation methods resulted in increased BAL concentrations of CCL2 (MCP-1), CCL5 (RANTES), CXCL1, CXCL10 (IP10), IFN-α, IFN-γ, and TNF." (PMID 31163619, 2019).
infection (continued). "T cell cytokines IFN-γ and IL-12, and chemokine CCL5 (also known as Regulated upon Activation, Normal T cell Expressed, and Secreted, or RANTES) were maintained into the convalescent phase of infection (10–35 days POS)." (PMID 31382545, 2019). "A substantial decrease in IL-6, IL-9, IL-12p40/p70, IL-13, IL-17, IFN-γ, CCL5, SCF, TNF-α, TPO, and vascular endothelial growth factor (VEGF) was observed across days 4 through 7 of NTHi infection." (PMID 31548315, 2019). "Among its target genes, we observed increased expression of IL6, IL8, CCL5 and CXCL10 at different time points post infection." (PMID 31575039, 2019). "pDCs are capable of producing various chemokines such as CCL4, CCL5, and CXCL10, which attract T cells to sites of infection and inflammation." (PMID 30984181, 2019). "Regarding the contribution of CCL3 to hRSV infection, it was shown that equivalent to CCL5, CCL3 displays a biphasic expression both for mRNA and protein, at day 1 and 7 post-infection." (PMID 30936869, 2019). "For instance, Th1 cells express high levels of CCR5 but also produce MIP-1α (CCL3), MIP-1β (CCL4) and RANTES (regulated upon activation normal T-cell expressed and secreted) (CCL5), the natural ligands for CCR5, thereby limiting R5 infection in these cultures." (PMID 31487324, 2019). "Lower parasite load in the cardiac tissue resulted in decreased levels of CCL5, a chemokine that is important for the recruitment of both CD4+ and CD8+ T cells effector cells to the site of infection." (PMID 31197200, 2019). "CCL5 expression were significantly decreased in PK-15 cells treated with rapamycin plus 107, 108 CFU/mL of SH0165 compared with SH0165 infection alone." (PMID 31106159, 2019). "Especially the chemokines CCL3, CCL5, and CCL11 increased in the lower infection groups 3 months after treatment." (PMID 30619332, 2018). "The expression of CCL5 and CXCL10 initiates peripheral leukocytes recruitment at the site of infection leading to aggravated inflammatory response, which has the deleterious effect on neurons." (PMID 30001342, 2018). "The low responders, Ghs6 and M15.2 (respectively), differ especially due to the downregulation of one or more of these genes, STAT1, CCL5, and IRF1, was predicted to increase viral replication and infection in the Ghs6 and M15.2 sublines." (PMID 29535762, 2018). "Immature DCs express the chemokines CCR1, CCR2, CCR5, CCR6, and CXCR1, thereby facilitating the arrival at the site of inflammation, infection and being able to recognize chemo-attractants, such as MIP-3 alpha/CCL20, RANTES/CCL5 and MIP-1 alpha/CCL3." (PMID 30297662, 2018). "In responses to VACV-70, HSV-60, dsDNA, and cGAMP, Trim29-/- macrophages also produced significantly elevated CCL5 and CXCL10, the chemokines that are important to recruit immune cells to the site of infection and eliminate viral infection." (PMID 29581886, 2018). "At pre-treatment, the chemokines CCL5, CCL11, and CCL17 were readily detected in all infection groups and the frequencies of responders were similar to the egg-negative individuals." (PMID 30619332, 2018). "In addition to lipocalin-2, equine MSCs from all sources examined expressed the immunomodulatory genes, MCP-1, IL-6, IL-8, and CCL5, suggesting that these cytokines may contribute to the reported ability of equine MSCs to limit infection indirectly by recruiting and activating immune cells." (PMID 30044182, 2018). "The concentration of CHI3L1 was determined together with key infection or inflammation parameters at the local level (bacterial load, neutrophil influx, interleukin (IL)-8 and IL1beta, IL-6, RANTES/CCL5 levels)." (PMID 29892291, 2018). "We found mRNAs of the type 1 chemokine ligands and their receptors (CCL4, CCL5, CCR5, CXCL9, CXCL10, CXCL11 and CXCR3) were increased at 21–28 days post-infection compared to uninfected controls." (PMID 28103263, 2017).
infection (continued). "During an infection with another alphaherpesvirus, HSV-1, in mice, it has been reported that CCL3 attracts NK cells, CCL2 recruits monocytes, and CCL5 recruits monocytes, NK cells, and PMNs while CXCL9 recruits T-cells to the sites of infection." (PMID 28241864, 2017). "For A549 cells and MDM, the induction of IL-6 and CCL5 was greater during infection with NH1125B than NH1067B at both 18 and 24 hours post-infection." (PMID 28877226, 2017). "After super-infection, mRNA levels of IL-6, TNFα, CCL3 and CCL5 were substantially increased, especially at 8 h p.i.." (PMID 28195157, 2017). "In response to infection with hRSV, human AEC-derived cell lines secrete cytokines and chemokines in vitro, including IL-6, IL-8, CCL2, CCL3, and CCL5 that promote the recruitment of monocytes and eosinophils to the site of infection." (PMID 29230219, 2017). "After infection, NK1.1+ cell depleted-mice exhibited significantly reduced levels of the cytokines IL-6, IL-12p40, and G-CSF, and of the chemokines CCL2 and CCL5 compared to mock-treated infected mice (P < 0.05)." (PMID 28706510, 2017). "It has been reported that infection of alveolar epithelial cells with influenza A virus can strongly induce the release of monocyte chemoattractants CCL2 and CCL5 followed by a strong recruitment of monocyte transepithelial migration." (PMID 28241864, 2017). "Changes in mesothelial cell gene expression of CCL5, TLR4, TNF, ZFP36, EDN1 and ITLN1 1 hour after infection with S. epidermidis." (PMID 28542390, 2017). "In conclusion, we have demonstrated that a basal to apical migration of CD172a+ cells in nasal mucosa was present during infections with neurological EHV-1 strains, with CCL2 and CCL5 involved in the attraction of CD172a+ cells towards the infected regions." (PMID 28241864, 2017). "In contrast, CK/SD/w3 has more capacity in inducing CCL-5 and CXCL-10 at the later stage of infection." (PMID 27446066, 2016). "Platelet-derived chemokines such as RANTES (CCL5) and platelet factor 4 (CXCL4, PF4) are well-known molecules responsible for neutrophil recruitment to sites of inflammation/infection." (PMID 27458459, 2016). "Infection of epithelial cells by IFV increases the expression of TNF-α, IL-6, IL-8, CCL2 (MIP-1), CCL5 (RANTES), CCL3 (MIP-1α), and CXCL10 (IP-10)." (PMID 28066442, 2016). "Critically, on day 4 post-infection, IL-1β, TNFα, IL-6, CCL2 and CCL5 concentrations were significantly reduced in BAL fluid while IL-6 and IL-18 were reduced in the sera." (PMID 27283237, 2016). "CHPV infection of PBMC, Monocytes and B cells strongly stimulated the chemokines (CCL2/MCP-1, CCL5/rantes, CXCL9, CXCL10/IP10) during the course of infection." (PMID 27628855, 2016). "Infection activates a broad chemokine response to infection, including CXC (CXCL1, CXCL5, CXCL8, CXCL9, and CXCL10) and CC chemokines (CCL2, CCL3, and CCL5)." (PMID 26927188, 2016). "Other chemokines, such as KC (CXCL1) and Rantes (CCL5), were also differentially expressed in A20AEC-KO and control A20WT mice at day 8 post-infection, although at lower levels." (PMID 26815999, 2016). "Our data clearly show an increased expression of a set of chemokines (CCL20, CCL5, CXCL1, CXCL10, CXCL11, CCL25) normally involved in H. pylori gastritis at both 6 and 18 weeks of infection in mice, which decreased after curcumin treatment." (PMID 25569625, 2015). "Specifically, cytokines and chemokines including IL-6, IL-8, TNF-α, as well as CCL-5, MIP-3α, and IP-10 were significantly induced, providing an immunopathological basis for liver pathology, deteriorated by infection-induced apoptosis." (PMID 26134299, 2015). "Ccl3, Ccl5, Tnfa, and Il6 were expressed at modest levels in unprimed RAW 264.7 cells upon infection, whereas pre-treatment of cells with IFN-γ strongly enhanced HSV1-induced gene expression." (PMID 25268627, 2014).
infection (continued). "Elevated levels of CCL3, CCL4, CCL5 and CXCL9 mRNA were detected in the livers of both WT and WSX-1−/− mice on day 7 of infection, whereas CCL3, CCL4, CCL5 and CCL20 mRNA levels were increased on day 14 of infection." (PMID 24244314, 2013). "Accordingly, IEC isolated from IFNγ−/− neonatal mice did not significantly upregulate the expression of CXCL9 and CXCL10 during the infection whereas other chemokines such as CCL3, CCL4 and CCL5 were still upregulated." (PMID 24367259, 2013). "Induction of IFN-λ1, and ISGs CCL-5 and CXCL-10 was significantly higher in COPD pBECs after infection compared to that in healthy pBECs." (PMID 23384071, 2013). "The chemokines CCL2, CCL5, CXCL1 as well as CXCL10 are all important for recruiting immune cells to the site of infection, and by inhibiting their biological activity, P. gingivalis is able to modulate and diminish the level of infiltrating immune cells." (PMID 23841502, 2013). "CD4+ T cells removed from anti-CCL5- and TAK779-treated mice also exhibited unimpaired migration to infection-derived liver cells when placed in a transwell assay in vitro." (PMID 24244314, 2013). "Cytokines and chemokines such as CCL2 (MCP-1), CCL3 (MIP1α), CCL5 (RANTES), and CXCL10 (IP10) are responsible for activating leukocytes and attracting them to the lung compartment to clear infection." (PMID 23441208, 2013). "IEC isolated from neonates at the peak of the infection presented a clear up-regulation of XCL1, CCL3, CCL4, CCL5, CXCL9, and CXCL10 expression, with levels close to those in adults for CXCL9 and CXCL10." (PMID 24367259, 2013). "An up-regulation of Ccl3, Ccl4, Ccl5, and Tgfb, a strong CD4+ T-cell response, and down-regulation of Il17, Il21 and Il23 occurred during infection." (PMID 23383148, 2013). "After infection, CCL12 (Figure B2-4) and CCL5 (B6) expression was induced in the ependyma in comparison to mock-infected samples." (PMID 22731103, 2012). "In vitro infection of immature dendritic cells (imDC) with DENV-2 led to induction of CCL11/Eotaxin, CCL2/MCP-1, CCL5/RANTES, CCL3/MIP-1α and CXCL10/IP-10." (PMID 22815692, 2012). "The list of genes with the greatest induction following Mtb:Δ-sigH infection at this time-point included CXCL1 (120-fold), PTGS2 (100-fold), CXCL6 (75-fold), CCL2 (53-fold), CXCL3 (40-fold), CXCL1 (43-fold) and CCL2 (38-fold) CCL5 (35-fold)." (PMID 22235255, 2012). "Cytokines like CCL5, small inducible cytokine A2, IL8 and other immune responsive genes like STAT1, IRF1 and B2 M were found to be up-regulated at this time point post infection with seasonal influenza virus." (PMID 21439068, 2011). "In the macaque model, infection with the 1918 Spanish influenza virus markedly increased serum levels of IL-6, IL-8, MCP-1, and RANTES (RANTES; CCL5)." (PMID 21375734, 2011). "In summary, up-regulation of mRNA for TNF-α, CCL-5/RANTES, and CXCL-10/IP-10 was found to be more prominent during the early phase of infection with H5N1/2004 and H9N2/1997 viruses than those induced by H1N1/2002 virus." (PMID 21108843, 2010). "In summary, at the late phase of infection (i.e. 18 and 24 hours post-infection), TNF-α, IL-6, IL-8, CCL-5/RANTES and CXCL-10/IP-10 mRNA remained at high levels for H5N1/2004 and H9N2/1997; which were in contrast to those observed for H1N1/2002." (PMID 21108843, 2010). "At 3 hours post-H5N1/2004 infection, there were 2-5 folds increase in the expression of TNF-α and CCL-5/RANTES." (PMID 21108843, 2010). "In contrast, in X4LAI.04-infected tissues production of CCL3, CCL4, CCL5, CXCL10, and CXCL12 was significantly increased compared with that in uninfected tissues and reached a maximum 5 to 9 days post-infection." (PMID 20862220, 2010). "In general, H5N1/2004 showed a higher capacity in inducing CXCL-10/IP-10 and CCL-5/RANTES as compared with that of H1N1 and H9N2; and the effects were more prominent at the late phase of infection, particularly at 24 hours post-infection." (PMID 21108843, 2010).